FASN (fatty acid synthase)
Diseases named in the same sentence as FASN in open-access papers (continued):
Sharing a sentence is not in itself a finding about the gene and the disease.
breast cancer (continued). "Herein, we questioned the role of fatty acid synthase (FASN), a lipogenic enzyme linked to HER2-driven breast cancer aggressiveness, in the development and maintenance of hormone-independent growth and resistance to anti-estrogens in ER/HER2-positive (ER+/HER2+) breast cancer." (PMID 33800852, 2021). "Akt isoform specificity has yet to be extensively studied in breast cancer in relation to FASN, although prostate cancer studies have revealed a relationship between Akt3 and FASN involving the two as downstream effectors of peroxisome proliferator-activated receptor gamma (PPARG) activation." (PMID 34298660, 2021). "Interestingly, another PPI omeprazole was shown to block the FASN and dose-dependently suppress breast cancer cell metastasis." (PMID 35003369, 2021). "Increased de novo FA biosynthesis and FASN upregulation has also been observed in breast cancer, melanoma, and hepatocellular carcinoma, and de novo FA biosynthesis and lipogenesis has been shown to be essential for protein palmitoylation of Ras, Wnt, calnexin, and Src in proliferating cells." (PMID 34606827, 2021). "In summary, a novel FASN-driven facet of the mitochondrial priming mechanistically links the redox-buffering mechanism of FASN activity to the intrinsic apoptotic threshold in breast cancer cells." (PMID 34675185, 2021). "CYH33 induces immune activation and synergizes with FASN inhibitor to further promote the antitumor immunity, which gains novel insights into how PI3K inhibitors exert their activity by modulating TME and provides a rationale for the concurrent targeting of PI3K and FASN in breast cancer treatment." (PMID 34373258, 2021). "For example, FASN can promote the growth of breast cancer and prostate cancer cells." (PMID 33789749, 2021). "We now reveal that FASN could be involved as an intrinsic factor of the transition to endocrine resistance in ER+/HER2+ breast cancer." (PMID 33800852, 2021). "And it has been reported that the mTOR inhibitor rapamycin could reduce the expression of FASN in breast cancer cells." (PMID 35071325, 2021). "We then explored whether the acquisition of FASN overexpression/hyperactivity might serve as part of the HER2-driven endocrine resistance program in ER+/HER2+ breast cancer cells." (PMID 33800852, 2021). "Yet, the contradictory results of FASN expression in breast cancer indicated in these two studies need further verification to see whether the effect of leptin varies in time-dependent or dose-dependent manner." (PMID 34888248, 2021). "FASN is a biological determinant of HER2-driven endocrine resistance in ER+ breast cancer." (PMID 33800852, 2021). "What’s more, enzymes involved in lipid metabolism may also be suitable targets for preventing the formation of brain metastases, such as FASN, which is a promising target for the treatment of brain metastasis originated from breast cancer." (PMID 35071325, 2021). "Next-generation, clinical-grade FASN inhibitors may be therapeutically relevant to countering resistance to tamoxifen in FASN-overexpressing ER+/HER2+ breast carcinomas." (PMID 33800852, 2021). "Although knowledge regarding FASN in radiation resistance is limited, it has been reported that FASN overexpression could render pancreatic and breast cancer cells resistant to radiation." (PMID 32944403, 2020). "Here, we tested the hypothesis that the PR-B and PR-A isoforms differentially modify the ability of prolactin to transcriptionally regulate the expression of the FASN gene in PR+ breast cancer cells." (PMID 33335078, 2020). "Because MCF-7 cells overexpressing HRG are estradiol-independent and acquire an anti-estrogen therapy-resistant phenotype, we explored whether exacerbated FASN activity might serve as part of the HRG-driven endocrine resistance program in breast cancer cells." (PMID 33081219, 2020).
breast cancer (continued). "By placing the lipogenic master regulator SREBP-1c as one of the select target genes coregulated by STAT5 and PR-B, we can explain the PR-B isoform-specific regulatory actions on the cross-talk between prolactin and FASN signaling in luminal breast cancer cells." (PMID 33335078, 2020). "However, little is known about how prolactin and FASN signaling interact during breast cancer progression." (PMID 33335078, 2020). "Our previous work, in breast cancer, reported that depletion of RhoU expression led to increased peripheral adhesions and reduced paxillin S272 phosphorylation; the same phenotype observed here in FASN knockdown cells." (PMID 32139877, 2020). "As macropinocytic breast cancers can scavenge fatty acids from necrotic cell debris, necrocytosis may reduce dependence on FASN and thus sensitivity to FASN inhibitors (FASNi)." (PMID 32111826, 2020). "Notably, FASN was found to be expressed highest in HER2-positive breast cancer and lowest in TNBC at both cell and tissue levels." (PMID 33489906, 2020). "As for CPT1A, all breast cancer tissues were characterised by extremely high enzyme expression; however, a slight but significant decrease in H-score was observed in the HR- subtypes—similarly to FASN." (PMID 32899149, 2020). "With respect to increased LDs in response to exogenous supplementation with oleic acid, this cellular response appears to be similar to that with fatty acid synthase (FAS) inhibitors along with mTOR inhibitors which results in synergistic toxicity in breast cancer cells." (PMID 32492043, 2020). "Similarly, FASN inhibition in breast cancer and non-Hodgkin lymphoma cell lines exhibits impaired glycolysis process." (PMID 32872164, 2020). "Perhaps more importantly, we now show that FASN is a key biological determinant of the molecular program through which HRG overexpression promotes the acquisition of an endocrine-resistant phenotype in ER+/HER2− breast cancer cells." (PMID 33081219, 2020). "FA synthase (FASN) overexpression induces resistance to anti-tumoral drugs such as doxorubicin and mitoxantrone in breast cancer cells, docetaxel resistance in HER2-positive breast cancer, gemcitabine resistance in pancreatic cancer, and cisplatin resistance in ovarian cancer." (PMID 33092283, 2020). "Deregulated lipid metabolism and enhanced FA synthesis have been described in different types of breast cancer: for example, FASN can be upregulated by HER2 signalling and induced by sterol regulatory element-binding protein 1 (SREBP1) under the control of mTOR." (PMID 32899149, 2020). "It has been assumed that a two-way regulatory system between FASN and HER2, the “HER2-FASN axis”, may enhance breast cancer proliferation, metastasis and chemoresistance." (PMID 33489906, 2020). "We first assessed how PR-B and PR-A isoforms could modify the ability of prolactin to regulate the expression of the FASN gene in PR+ breast cancer cells." (PMID 33335078, 2020). "Accordingly, therapeutic blockade of FASN activity may be effective in the prevention of refractoriness to endocrine therapy in HER2-negative breast carcinomas subtypes where FASN overexpression results from HER2/HER3 signaling." (PMID 33081219, 2020). "Interestingly, many studies have shown the interplay between FASN and cellular localization of Her-2 oncogene in breast cancer cells." (PMID 31030489, 2019). "In addition, the FASN-targeting drug cerulenin can dose-dependently decrease HER2/neu protein levels in breast cancer cells (from a 14% decrease at 1.25 mg/L to a 78% decrease at 10 mg/L), and it has been suggested as a possible anticancer treatment." (PMID 30872976, 2019). "Fasnall, a thiophenopyrimidine-based FASN inhibitor with potent and broad antitumor activity against various breast cancer models, might represent a promising alternative." (PMID 31921669, 2019).
breast cancer (continued). "Furthermore, metformin decreased FASN protein levels in breast cancer cells and the FASN inhibitor orlistat up-regulated AMPK activity in lung cancer cells." (PMID 30774777, 2019). "Moreover, FASN inhibitors (C75, cerulenin) and FASN siRNA treatments have been shown to induce apoptosis in breast cancer cells overexpressing FASN." (PMID 31477154, 2019). "A previous study decreasing FASN and FABP1 cause inhibition of EMT in breast cancer cells." (PMID 30388870, 2018). "If caveolin-1 acts as a pro-invasive switch combined downregulation of caveolin-1 and FASN/ERα signalling might be necessary to effectively suppress cell growth and prevent invasion in a specific subset of ERα-positive breast cancer patients." (PMID 29331414, 2018). "The collection was screened for cytotoxicity and FASN inhibition against a HER2-positive human breast cancer cell line overexpressing FASN, and three lead compounds were identified, G28, G37, and G56, which improved the properties of their precursor molecule EGCG without affecting mice body weight." (PMID 29751678, 2018). "In breast cancer, a high demand of FA from de novo synthesis has been reported as a response to the overexpression of several enzymes, such as fatty acid synthase (FASN), acetyl-CoA carboxylase (ACC) and ATP citrate lyase (ACLY)." (PMID 29438405, 2018). "Furthermore, we reveal the pro-invasive consequences of targeted inhibition of FASN and ERα signalling in ERα-positive breast cancers and we provide evidence for the therapeutic potential of caveolin-1 in this specific context." (PMID 29331414, 2018). "Indeed, the cytotoxic effects of EGCG’s targeting inhibition of FASN activity has been reported in breast cancer cells." (PMID 29588626, 2018). "Notably, pharmacological FASN blockade using sub-optimal concentrations of C75 greatly increased E2-dependent ERα activity in all three-breast cancer models." (PMID 28240737, 2017). "As in more differentiated breast cancer cells, FASN expression appears upregulated in breast CSCs, while in ovarian ALDH+/CD133+ CSCs (OCSCs), a higher grade of unsaturated lipids has been found inside LDs, compared to non CSCs, by using Raman microspectroscopy and mass spectrometry." (PMID 28883835, 2017). "The stage IV-specific biomarker FASN is a protein that is involved in cellular fatty acid metabolism and that is reportedly involved in different cancer types, including ovarian cancer and breast cancer." (PMID 28984208, 2017). "FASN activation is required for estrogen-mediated signaling in ER+ breast cancer cells." (PMID 29228577, 2017). "FASN up-regulation has been observed in breast cancer, melanoma, and hepatocellular carcinoma." (PMID 28962653, 2017). "PCa vs control comparisons revealed some startling increases of mRNA levels of: ETV1, a gene that directs androgen metabolism and confers aggressive PCa; FASN, a fatty acid metabolism gene highly up-regulated in PCa; RBM39, a gene implicated in colorectal and breast cancer progression." (PMID 28143451, 2017). "In this context, several reports highlight that FASN overexpression could be a putative biomarker and therapeutic target in several carcinomas, including breast cancers." (PMID 29088795, 2017). "Inhibition of FASN phosphorylation decreased invasion by SK-BR-3 and BT-474 breast cancer cells." (PMID 28412757, 2017). "Our results suggest a novel mechanism through which pharmacological blockade of FASN-catalyzed endogenous lipogenesis might promote an ERα-related suppression of E2-stimulated breast cancer cell growth and survival." (PMID 28240737, 2017). "Thus, in the following studies, we focused on exploring miR-15a-16-1-mediated FASN expression in breast cancer cells." (PMID 27713175, 2016). "Here, we hypothesized that co-expression of FASN, COX-2, and OPG might be responsible for poor prognosis breast cancer and adds to the severity and malignancy associated with breast cancer." (PMID 27270654, 2016).
breast cancer (continued). "Interestingly, knockdown of OPG by CRISPR/Cas9 gene editing in breast cancer cells also decreased the FASN protein levels." (PMID 27270654, 2016). "Thus, inhibiting FASN expression or its activity represents a promising approach of therapeutic treatment for multiple cancers, including breast cancer." (PMID 27713175, 2016). "In agreement with earlier reports on the up-regulatory effects of androgens, progestins, growth factors, growth factor receptors, and hypoxia on FASN gene activity, CCN1- stimulated FASN expression seems to involve activation of the SREBP pathway in breast cancer cells." (PMID 27713913, 2016). "Interestingly, knocking down OPG by CRISPR/Cas9 gene editing in breast cancer cells decreased FASN expression at the protein level." (PMID 27270654, 2016). "There was consistent elevated expression of FASN throughout the breast cancer tissue samples." (PMID 27270654, 2016). "We speculate that altered expression of miRNAs is one important mechanism by which FASN expression is deregulated in breast cancer." (PMID 27713175, 2016). "Fatty acid synthase (FASN) is upregulated in breast cancer and correlates with poor prognosis." (PMID 27713175, 2016). "We demonstrated that breast cancer cells express abundant levels of FASN and ACC1." (PMID 26621841, 2016). "Some of these genes may play a role in mammary oncogenesis; thus, restoration of FASN expression only partially rescues proliferation of breast cancer cells." (PMID 27713175, 2016). "The inconsistency for the activity of miR-195 in regulating FASN expression between our study and a previous report is likely due to some subtle difference between breast cancer and osteosarcoma, such as difference in cellular protein composition and microenvironment." (PMID 27713175, 2016). "This suggests that other mechanism may play a role in maintaining the equilibrium of FASN levels in breast cancer cells." (PMID 27713175, 2016). "Likewise, specific inhibition of FASN was shown to sensitize cisplatin-resistant breast cancer cells to cisplatin." (PMID 27765901, 2016). "Taken together, our study represents proof of principle that anticancer effects can be obtained with strategies to deprive tumors of leucine via suppressing FASN expression, which provides important insights in prevention of breast cancer via metabolic intervention." (PMID 27579768, 2016). "The overexpression of FASN has been associated with poor prognosis and may be a novel therapeutic target in HER2-overexpressing breast cancer cells." (PMID 26892392, 2016). "FASN a multifunctional enzyme plays a key role in biosynthesis of fatty acid and ACACA is known to specifically interact with the protein coded by one of the major breast cancer susceptibility genes BRCA130." (PMID 26632252, 2015). "Furthermore, the activated mTOR pathway promoted FASN expression, which results in the malignant phenotype transformation of breast cancer cells." (PMID 24866893, 2014). "This suggested that FASN expression was more closely associated with HER2 expression than with ER expression in breast cancer cells, whereas mTOR expression was independent of HER2 and ER status." (PMID 24866893, 2014). "Conversely, the absence of S14 from PyMT-induced mammary tumors was associated with slower tumor growth and decreased proliferation, which was coincident with decreased FASN activity and lower levels of MCFA in tumors lacking S14 compared to controls." (PMID 25472762, 2014). "Although the requirement of FASN for breast cancer cell survival and proliferation has been established in vitro and in xenograft models, it is not known whether elevated fatty acid synthesis is sufficient to promote cancer metastasis." (PMID 25472762, 2014).
breast cancer (continued). "We cloned the 680-bp human FASN Promoter I region from the human genome into the pGL3-enhance vector to construct a pGL3-FASN recombinant luciferase reporter vector; this vector has been previously shown to exhibit high transcriptional activity in FASN-overexpressing breast cancer cells." (PMID 24866893, 2014). "And the transcriptional activity of FASN promoter was high in ER+/HER2+ breast cancer cells." (PMID 24866893, 2014). "In this study, we found that FASN was overexpressed in ER+/HER2+ breast cancer cells." (PMID 24866893, 2014). "FASN expression has been reported to be regulated by the human epidermal growth factor receptor HER2 oncogene (erbB2) through phosphatidylinositol 3-kinase (PI3-K)/Akt in breast cancers as well as by mTOR signaling pathways in colorectal cancer cells." (PMID 25255125, 2014). "Furthermore, rapamycin (2.5 nmol/L, 4 h) down-regulated FASN mRNA expression in all three breast cancer cell lines." (PMID 24866893, 2014). "Moreover, it has been reported that FASN expression is induced in response to hypoxia through the activation of Akt and SREBP1, and high levels of FASN expression were found in hypoxic regions of breast cancer xenografts." (PMID 24203995, 2013). "Furthermore, FASN mRNA levels were over 6-fold lower in both breast cancer cell lines compared to 184B5 cells (0.15-fold compared to 1-fold, respectively, p < 0.0001)." (PMID 21294903, 2011). "Taken together, these data suggest that inhibiting FASN activity may be a new therapeutic strategy in breast carcinomas with acquired resistance to anti-HER2 therapies." (PMID 22177475, 2011). "Finally, the effects of estradiol treatment and FASN inhibition on Mb expression in breast cancer cells were analysed." (PMID 20531416, 2010). "Our results support the hypothesis that HER2-mediated FASN phosphorylation plays an important role in breast cancer progression and may be a novel therapeutic target in HER2-overexpressing breast cancer cells." (PMID 21080941, 2010). "FASN overexpression also confers resistance to Adriamycin and mitoxantrone in breast cancer cells." (PMID 19352381, 2009). "We then tried human breast cancer cell line MCF-7 that is shown to express high levels of FASN." (PMID 18523653, 2008). "Some previous studies on CER impacts with cancer drugs, such as trastuzumab/breast cancer, 5-FU/breast cancer, and temozolomide + radiotherapy/glioblastoma, showed increased drug effectivity; these studies commonly found changes in signaling pathways and ER stress with FASN inhibition." (PMID 40133683, 2025). "Also, upregulated FASN expression and activities were detected in brain metastasis of breast cancer, which was evidenced by the detection of FASN mRNA and lipid products, such as monosaturated fatty acids (e.g., triacylglycerols), in brain metastasis of BT-474 breast cancer cells in mice." (PMID 40214422, 2025). "In addition, cisplatin also decreased FASN expression and increased apoptosis of breast cancer cells, suggesting that the combination of FASN inhibitors and cisplatin may improve the prognosis of cancer patients." (PMID 39757995, 2025). "In addition, FASN expression was positively correlated with a signature corresponding to the top 100 CRISPR-mediated gene dependencies similar to FASN identified in the Cancer Cell Line Encyclopedia (breast cancer TCGA PCC = 0.30, p = 4 × 10−24; pan-cancer TCGA PCC = 0.75, p < 10−16)." (PMID 39349429, 2024). "However, fatty acid transporters such as CD36, FATP3, and FATP4 were undetectable in the breast cancer cell lines used (unpublished observations), indicating that their expression level in breast cancer cells likely had minimal contribution to FASN regulation of p65 expression." (PMID 38467328, 2024). "Therefore, we further analyzed the spatial expressions of ACC and FASN in breast cancer tissues." (PMID 37120513, 2023). "Furthermore, FASN promotes breast cancer metastasis by mediating changes in specific fatty acids." (PMID 36674685, 2023).